STAT6 (signal transducer and activator of transcription 6)
Diseases named in the same sentence as STAT6 in open-access papers (continued):
Sharing a sentence is not in itself a finding about the gene and the disease.
tumor (continued). "STAT6 in vitro data suggested a role of the IL-4/STAT6 in disease relapse by providing a favorable niche for the clonogenic growth of tumor-inducing PCa cells." (PMID 35207527, 2022). "STAT6 regulates the balance of Th1 and Th2 cells, which promotes tumor growth by allowing tumor cells to evade immune responses." (PMID 35401182, 2022). "STAT6 expression is elevated in PCa compared to benign prostate, while STAT6 expression correlates with higher GS and larger tumor size." (PMID 35207527, 2022). "In the tumor xenografts model, inhibition of STAT6 activation reduced tumor angiogenesis and NRP1 expression, suggesting the therapeutic potential of STAT6 inhibitors." (PMID 35600336, 2022). "Because STAT6 protein was expressed by both tumor cells and macrophages, we specifically analyzed the expression of STAT6 in IBA1+ (Ionized Calcium-Binding Adapter Molecule 1) macrophages within the tumor areas." (PMID 35179953, 2022). "Variants known to be associated with FL pathogenesis such as STAT6 p.D419 or EZH2 p.Y646 were observed in patient-matched cfDNA and tumor tissue samples." (PMID 35795062, 2022). "Moreover, engineered exosomes delivering an antisense oligonucleotide targeting STAT6 can selectively silence STAT6 expression in tumor-associated macrophages (TAMs), which may help us to reprogram TAMs toward a pro-inflammatory M1 phenotype to heighten CD8+ T cells efficacy in the TME." (PMID 36011030, 2022). "Earlier we have demonstrated that the inhibition of STAT6 in M2 macrophages only hampered the M2-induced tumor cell migration as shown in in vitro cultures using conditioned media and in vivo in 4T1 tumor model." (PMID 35927238, 2022). "The mechanism of action of STAT6 in tumorigenesis is being gradually understood, but is still unclear in with respect to tumor angiogenesis." (PMID 35600336, 2022). "Our study elucidated that SOX21-AS1 played a tumor promoting role in PC, and a mechanism was further revealed whereby STAT6-activated SOX21-AS1 promoted PC cell malignancy via up-regulation of SOX21." (PMID 36335356, 2022). "In the TME, high levels of IL-4 produced by CD4 T cells, tumor cells, and other cell types drive the immunosuppressive phenotype of TAMs through the STAT6 pathway." (PMID 35179953, 2022). "In tumor xenograft models, inhibition of STAT6 reduced xenograft growth, tumor angiogenesis, and NRP1 expression in vivo." (PMID 35600336, 2022). "Immunohistochemistry staining (magnification, ×400) showed that the tumor cells were positive for STAT6, CD34, Ki67 (10%), CD99, Bcl2, and Vimentin." (PMID 36386546, 2022). "STAT6 can influence tumor angiogenesis through factors such as VCAM-1 and MMP, and NRP1 is not the only target molecule of STAT6." (PMID 35600336, 2022). "The group contains seven members, of which STAT3, STAT5, and STAT6 are involved in tumor progress, metastasis, and therapy resistance." (PMID 35207527, 2022). "TAMs from Stat6−/− tumor-bearing mice display an M1 phenotype and demonstrate enhanced rejection of various tumor types, consistent with the role of STAT6 in polarizing TAMs to an M2 phenotype." (PMID 35179953, 2022). "The role of signal transducer and activator of transcription 6 (STAT6) in tumor growth has been widely recognized." (PMID 35600336, 2022). "Histopathologic examination of the excised tumor showed in-toto resection (R0) and STAT6 positive tumor cells with more than 10 mitoses per HPF and a Ki-67 index of 15–20% indicating recurrence of a higher grade SFT/HPC (WHO grade III)." (PMID 36421340, 2022). "Interestingly, these tumor growth inhibition effects may be associated with STAT6 inhibition." (PMID 34861103, 2022). "Anti‐Chi3L1 antibody inhibits tumor growth and metastasis through STAT6‐induced M2 polarization inhibition and PLG expression." (PMID 34861103, 2022).
tumor (continued). "Research has also discovered that LILRB2 expressed on tumor-associated myeloid cells inhibited the activation of SHP1/2, AKT and STAT6, leading to restraint of the function of M1-like macrophages and promotion of the function of M2-like macrophages." (PMID 35321724, 2022). "In our study, AS1517499 administration for both HUVECs and nude mouse xenograft showed that inhibition of STAT6 reduced proliferation, migration, and tube-formation of HUVECs and reduced tumor size and tumor angiogenesis in a mouse xenograft model." (PMID 35600336, 2022). "Previously, to study the role of STAT6 pathway in vivo, we used 20 mg/kg dose of AS in which we observed a slight inhibition of the tumor growth and a major reduction in the lung premetastatic niche formation." (PMID 35927238, 2022). "In macrophages or tumor cells, the transcription factor STAT6 or NF-kB is reported to be involved in inducing GDF15 expression." (PMID 34877504, 2021). "A recent study found that in lung cancer, IL-4 secreted by M2-myeloid cells and tumor cells activate the STAT6 pathway and promote M2 polarization and tumor progress." (PMID 34925244, 2021). "Combinations of IGF-1, NFAT or STAT6 inhibitors with CSF-1R inhibitors partially prevented tumor recurrence." (PMID 34949203, 2021). "STAT3, like STAT5 and STAT6, affects the tumor microenvironment (TME), boosting immunosuppressive TMEs and decreasing anti-tumor immunity." (PMID 34952583, 2021). "Conversely, WT mice showed an inverse frequency of Treg cells compared with STAT6−/− mice, which was followed by intestinal tumor formation." (PMID 33919941, 2021). "At early stages of the CAC induction, tumor-bearing WT mice only reached 9.8% of Treg cells, while STAT6−/− AOM/DSS mice reached 17.5% at the same time point of analysis." (PMID 33919941, 2021). "This treatment increased the number of T cells, eliminated TAMs, and reduced tumor growth in tumor-bearing mice by targeting the ILRα-STAT6 signaling pathway." (PMID 34207035, 2021). "In contrast, during the advanced stages of tumor development (Day 68), the Foxp3+ cells were significantly higher in the tumor-bearing WT mice, compared to the STAT6−/− AOM/DSS animals, (30.6 ± 7.3 vs. 5.6 ± 4.2, p < 0.001)." (PMID 33919941, 2021). "The fusion gene NAB2/STAT6 and its variants confirm a diagnosis of SFT in those cases with unconvincing STAT6 immunoreactivity, and specific gene fusions have been related to prognosis and tumor location." (PMID 34502329, 2021). "While these findings suggest the intrinsic importance of STAT6 in regulating tumor growth, our studies have found an important role of STAT6 in non-tumor cells for controlling tumor growth." (PMID 33919941, 2021). "Taken together, our results suggest that the Treg cell populations in the tumor microenvironment and peripheral organs prevent tumor progression in STAT6−/− mice." (PMID 33919941, 2021). "In studies ranging from lymphoma, melanoma, colorectal, breast, and lung cancer, STAT6 is overexpressed within the tumor microenvironment (TME) as an immunosuppressive signal to promote the function of M2 macrophages to assist in tumor growth and inflammation." (PMID 34012451, 2021). "As expected, the WT mice displayed both increased numbers of tumors as well as increased tumor load at Day 68 (9.6 ± 2.4), whereas only 30% of STAT6–/– animals developed tumors, and they were scarce (0.6 ± 1.3, p < 0.05)." (PMID 33919941, 2021). "On the contrary, the expression of TGF-β mRNA was increased in the colons of the tumor-bearing WT mice, compared to the STAT6−/− AOM/DSS animals, at Day 68 of the CAC progression (2.1 ± 0.2 vs. 0.5 ± 0.4; p < 0.01)." (PMID 33919941, 2021). "Previous studies reported that IL-13Rα1 can restrict tumor progression; IL-13 binding to IL-13Rα1 activates Stat6 which promotes caspase-3 mediated apoptosis." (PMID 33591997, 2021). "The results showed that the expression of STAT1, STAT2, STAT3, STAT5A, and STAT6 increased with increasing tumor grades." (PMID 34276757, 2021).
tumor (continued). "On the other side, the activation of M2 macrophage polarization is mediated by a predominance of STAT3 and STAT6, resulting in immune suppression and tumor progression." (PMID 33522932, 2021). "An early depletion of Treg cells during CAC development in STAT6−/− mice restores tumor growth, along with inflammatory infiltration in the colon." (PMID 33919941, 2021). "We found that the expression of STAT6 positively correlated with tumor grades and high levels of STAT6 predicted poor prognosis." (PMID 34276757, 2021). "Exosomes enriched in miR-29a-3p are transported to the unpolarized macrophages and are differentiated into M2-subtype through the activation of SOCS1/STAT6 signaling, eventually leading to invasion and tumor cell proliferation." (PMID 33522932, 2021). "M2aM2c has a regulatory/pro-tumoral behavior favoring tumor growth and tumor evasion, and it is promoted by turning on STAT6 from M1M2d." (PMID 34177892, 2021). "In the present case, the tumor was positive for STAT6, also showed high cellularity, increased mitotic figures (12/10 HPFs), nuclear pleomorphism (increased N/C ratio), necrosis inside the tumor, and invasive proliferative findings." (PMID 33188464, 2020). "This type of fusion leads to the development of STAT6 antibody, an immunohistochemical marker for this type of tumor." (PMID 32316178, 2020). "Extraordinarily high ORs/STAT6 ratios (> 15.0), observed only in six out of 117 cfDNA samples, point towards rare somatic copy number gains of these genes in some tumours." (PMID 32724107, 2020). "STAT6 is highly expressed in tumor cells and its level is positively correlated with a high rate of cell proliferation and poor prognosis." (PMID 33287240, 2020). "In contrast, M2 polarization, associated with immune suppression and tumor progression, is induced by STAT3 and STAT6 activation." (PMID 32133045, 2020). "IL-4-driven activation of STAT6 leads to the inhibition of TRIM24 activity in macrophages, supporting polarization of macrophages toward the tumor-associated phenotype in a murine model of melanoma." (PMID 32486098, 2020). "The mechanism of MPs stimulating M2 type macrophages and promoting tumor progression involves the activation of cGAS/STING/TBK1/STAT6 pathways in macrophages." (PMID 32983146, 2020). "In vivo studies substantiated the efficiency of siRNA in knocking down STAT6 and subsequent inhibition of tumor growth." (PMID 33287240, 2020). "Phosphorylated STAT3 and STAT6 together cooperated to increase cathepsin expression in TAMs resulting in the enhanced tumor invasion in vivo." (PMID 32486098, 2020). "We found that these adjuvant therapies induced a remarkable reduction of tumor growth when administrated together with 5-FU, correlating with a reduction in STAT6-phosphorylation." (PMID 32244885, 2020). "Immunohistochemical staining revealed that the tumor cells were positive for STAT6, CD34, CD99, and BCL2." (PMID 32638177, 2020). "The present case was finally diagnosed as a SFT of the pancreas because the tumor was positive for STAT6." (PMID 33188464, 2020). "We observed that tumor cells secrete lower levels of IL-4 after being cocultured with STAT6−/− CD11b+ cells, indicating that the pathway regulating IL-4 secretion pathway is inhibited by STAT6 deficiency in CD11b+ cells but not tumor cells." (PMID 31798581, 2019). "Emerging evidence shows that signal transducer and activator of transcription 6 (STAT6) plays critical roles in tumor development." (PMID 31798581, 2019). "IL-4 is consistently reduced in STAT6−/− CD11b+ cells compared to WT CD11b+ cells when cocultured with tumor cells." (PMID 31798581, 2019). "In stark contrast, in a model of sporadic inflammation-independent carcinogenesis this Stat6 controlled mechanism supports tumor promotion highlighting a so far unrecognized nuclear function of unconventionally activated Stat6 in IEC." (PMID 30353167, 2019).
tumor (continued). "Recently, a member of the STAT family, STAT6, has received considerable attention in the area of tumor growth and metastasis." (PMID 31798581, 2019). "Nuclear staining of STAT6 resulting from the translocation of the NAB2-STAT6 fusion protein to the nucleus is a gold-standard marker for the tumor." (PMID 30206803, 2019). "Taken together, these results indicate that CD11b+ cells from WT mice were related to tumor growth, while CD11b+ cells from STAT6−/− mice limited tumor growth." (PMID 31798581, 2019). "Signal transducer and activator of transcription 6 (Stat6) is the main transcription factor of interleukin-4 (IL-4) signaling and its participation in the development of various tumor types has been already reported." (PMID 30353167, 2019). "LncRNA-MM2P promotes M2 polarization of macrophages via reducing phosphorylation on STAT6, then affecting macrophage- mediated tumorigenesis and tumor growth." (PMID 31448238, 2019). "The STAT6 signaling pathway is highly activated in tumors and has been shown to promote tumor metastasis in colorectal cancer and melanoma carcinoma." (PMID 31798581, 2019). "Our data unravel unexpected IL-4-independent functions of Stat6 in chromatin compaction in intestinal epithelial cells ultimately providing both tumor suppressive as well as tumor promoting effects in different models of intestinal tumorigenesis." (PMID 30353167, 2019). "NAB2–STAT6 fusion was detected in 99 of 111 successfully tested tumors (89%) including the single STAT6 immunonegative tumor." (PMID 30584643, 2019). "Flow cytometry analysis showed increased CD11b+F4/80lowLy6ChighCD206− M1 cells and decreased CD11b+F4/80highLy6C−CD206+ M2 cells in both the lung and blood of STAT6−/− tumor-bearing mice." (PMID 31798581, 2019). "HE staining of whole-lung sections further confirmed the reduced tumor sizes and reduced inflammation response around tumor nodules in STAT6−/− tumor-bearing mice." (PMID 31798581, 2019). "Collectively, these data clearly support a tumor promoting function of Stat6 in IECs during early sporadic colorectal carcinogenesis." (PMID 30353167, 2019). "One of the most prominent signaling pathways responsible to skew immune cells towards a presumably tumor promoting type 2 profile comprises IL-4 receptor engagement and subsequent activation of signal transducer and activator of transcription 6 (STAT6)." (PMID 30353167, 2019). "STAT6 has a well-known role in tumour immunosurveillance, immune function and lymphomagenesis but has only recently been associated with cancer progression." (PMID 31075146, 2019). "In some tumor cells, cytokine IL-4 can act as a pro-survival signal factor and activate downstream STAT6 to begin responsive gene transcription for anti-apoptotic activity." (PMID 30890936, 2019). "A more recent study suggests that miR-135b functions as a tumour suppressor, affecting the metastatic ability of prostate cells by targeting STAT6, and STAT6 knockdown resulted in reduced cell metastasis." (PMID 31075146, 2019). "Taken together, our data suggest that STAT6 promotes cancer cell proliferation by altering tumor-macrophage interactions and IL-4 secretion." (PMID 31798581, 2019). "An examination of STAT protein expression levels showed that STAT6 levels were significantly lower in GSCs compared with non-tumor tissue, whereas levels of STAT1, STAT3 and STAT5 were significantly higher." (PMID 31530290, 2019). "Instead, it is STAT6 in CD11b+ cells that plays a relatively more important role in tumor cell proliferation." (PMID 31798581, 2019). "The metastatic tumor cells expressed elevated levels of Ki-67, and STAT6, but decreased levels of CD34 relative to those in primary tumor cells." (PMID 31321477, 2019). "The mean-SUV value by PET showed less F18 accumulation in the lung of STAT6−/− mice compared to WT mice, and relatively decreased lung tumor load was shown." (PMID 31798581, 2019).
tumor (continued). "Due to the critical tumor-promoting function of M2-like TAMs, we propose that targeting Trim24 or downstream Stat6 acetylation has clinical potential in cancer immunotherapy." (PMID 31554795, 2019). "CD8+ T cells are increased in STAT6−/− tumor-bearing mice, and decreased M2 and elevated CD8+ cytotoxic T lymphocytes exert a synergistic inhibitory effect on tumor proliferation in STAT6−/− mice." (PMID 31798581, 2019). "Immunofluorescence studies indicated that fewer pan macrophages (CD68+CD163+) are present in the lung of STAT6−/− tumor-bearing mice than their WT littermates." (PMID 31798581, 2019). "Bone marrow-derived macrophages from STAT6−/− mice and their WT littermates present different polarizations, which exert different effects on tumor growth." (PMID 31798581, 2019). "Importantly, also Stat6-deficient tumor epithelia were characterized by increased Stat3 phosphorylation suggesting that enhanced gp130-dependent Stat3 activation triggered by IL-6 and IL-11 could account for the pro-proliferative, pro-tumorigenic phenotype of Stat6−/− mice (data not shown)." (PMID 30353167, 2019). "By contrast, Stat6 mediates the suppression of TRIM24 expression in M2 macrophages to contribute to the induction of an immunosuppressive tumor niche." (PMID 31554795, 2019). "This study aimed to investigate the role of STAT6 and the interaction between STAT6 and the tumor microenvironment in pulmonary tumorigenesis." (PMID 31798581, 2019). "Significant reductions in the number and size of tumors were observed in primary tumor-bearing STAT6−/− mice compared to WT littermates." (PMID 31798581, 2019). "A detailed histological examination including immunohistochemical testing (STAT6 and β-catenin) and genetic testing (CTNNBB1 mutation) can be used to diagnose a tumor as GPC." (PMID 29168109, 2018). "Nevertheless, the tumor demonstrated strong immunoreactivity for STAT6, thereby indicating SFT, whereas CD34 was only weakly expressed." (PMID 30168002, 2018). "Up-regulation of let-7b is characteristic of prostatic TAMs (Tumor-associated macrophages), which targeting of the SOCS4 3′ untranslated region and inhibition of SOCS4 promoted phosphorylation of STAT3 and STAT6." (PMID 28948005, 2017). "The same group reported that survival of tumor bearing STAT6−/− mice and reduction in metastasis are dependent on the restored capacity of TAMs to produce tumoricidal NO." (PMID 28197019, 2017). "STAT3, STAT5, and STAT6 exhibit tumor-promoting functions, not only in cancer cells and cancer stem cells, but also in other cellular constituents of the tumor microenvironment, such as stromal cells and immune cells." (PMID 28903353, 2017). "The immunohistochemical analysis of paraffin-embedded sections prepared from this specimen revealed a diffuse positive STAT6 staining in the tumour cell nuclei." (PMID 28494796, 2017). "According to a recent report, STAT3 and STAT6 were shown to synergistically promote cathepsin secretion by macrophages, thereby enhancing tumour invasion and metastasis." (PMID 29065107, 2017). "Our previous study reported that STAT6 gene expression was down-regulated in the CD11b+ myeloid cells of HDC−/− tumor-bearing mice compared with the corresponding cells of WT mice." (PMID 28272448, 2017). "Together, these findings demonstrate that STAT3 and STAT6 cooperate in macrophages and enhance tumour progression in a cathepsin-dependent manner." (PMID 29065107, 2017). "Reduced activity of STAT6 in tumor-infiltrating ISCs of mice that received AdC68-mFAP together with AdC68-gDMelapoly most likely reflects vaccine-induced changes in cytokines or chemokines within the TME, which in turn recruit and activate ISCs." (PMID 26943036, 2016). "Cumulatively, these results suggest that IR-induced IL-4 regulates tumor progression by promoting β-catenin/Stat6 via activation of JAK and JNK." (PMID 27895317, 2016).